VDR (vitamin D receptor)
Diseases named in the same sentence as VDR in open-access papers (continued):
Sharing a sentence is not in itself a finding about the gene and the disease.
liver disease (continued). "In our recent work, we summarized the progress in understanding the molecular mechanisms involved in vitamin D–VDR signaling and discussed the functional significance of VDR signaling in specific cell populations in liver disease." (PMID 35955597, 2022). "Our study in Vietnamese patients chronically infected with HBV aimed to investigate the association of these VDR polymorphisms with susceptibility to HBV infection and liver disease outcomes." (PMID 31864292, 2019). "Compelling evidence indicates that vitamin D signaling and VDR variants have a significant implication on susceptibility to HBV infection and subsequent liver diseases." (PMID 31864292, 2019). "In this study, we examined the association of VDR polymorphisms TaqI, FokI, ApaI, and BsmI with HBV infection risk and with the progression of HBV-related liver diseases." (PMID 31864292, 2019). "OBJECTIVE: This study aimed to estimate the frequency of H. pylori infection in patients with liver disorders, and identify the relationship between vitamin D receptor gene variants and susceptibility to H. pylori infections and HCC in Egyptian patients with liver diseases." (PMID 41928106, 2026). "Also, the expression of Vitamin D receptors (VDR) decreases as the liver disease progresses, especially in the case of lobular inflammatory damage." (PMID 38542310, 2024). "VDR expression levels were related to the clinical severity of liver disease." (PMID 37511164, 2023). "Understanding the molecular mechanisms underlying the regulation of liver homeostasis by vitamin D and VDR may implicate vitamin D in a broad spectrum of liver disease pathogenesis." (PMID 35955597, 2022). "Recently, two studies published in Hepatology further emphasized the importance of VDR in regulating inflammatory response, and VDR activation by VDR ligands may be useful as a potential method for treating multiple liver diseases." (PMID 32296329, 2020). "However, the relationship between distinct VDR variants and HBV infection and liver disease progression has remained controversial." (PMID 31864292, 2019). "This study aims to investigate the potential role of VDR polymorphisms (TaqI, FokI, ApaI, and BsmI) in Vietnamese HBV infected patients and to correlate these polymorphisms with the progression of HBV-related liver disease." (PMID 31864292, 2019). "Levels also increase in HSCs and KCs with inflammation, and several immune functions of VDR described in other tissues may also be involved in liver disease." (PMID 29659559, 2018). "The influence of vitamin D metabolism on HBV-related liver diseases remains unclear and the role of vitamin D and its interaction with vitamin D receptor on the pathogenesis of HBV infection needs to be explored further." (PMID 27659316, 2016). "A major objective of this study was to investigate the biological role of VDR SNPs in patients with two closely related liver diseases and to test the hypothesis that these genetic factors may play distinct biological roles in the progression of HCV infection to cirrhosis." (PMID 37511164, 2023). "The correlation between the severity of ACLD and the deficiency of vitamin D could be explained by the fact that vitamin D improves portal hypertension through the activation of Vitamin D receptor (VDR) and Calcium-sensing receptor (CaSR) in a cirrhotic rats model." (PMID 36012285, 2022). "In conclusion, our results indicate that VDR polymorphisms are independently associated with the severity of liver cirrhosis and the survival of patients with liver disease, regardless of disease etiology, suggesting a potential influence of them in disease progression." (PMID 30218108, 2018). "The potent effect of VDR SNPs on VDR expression levels may play a role in liver disease progression, considering the observed inverse relationship between CD14+VDR+ cell levels and MELD score in the cirrhotic patients in our study." (PMID 37511164, 2023).
liver disease (continued). "Combining VDR rs2228570 A/A genotype with IL28B C/C genotype increased the probability of SVR from 82 % to reach 100 % and from 29 % to reach 80 % in C/T+ T/T IL28B genotype in none F4 liver disease patients." (PMID 26911666, 2016).
endometriosis (26 papers, 2011 to 2025). The growth of functional endometrial tissue in anatomic sites outside the uterine body. "This study investigated the association between vitamin D levels and endometriosis, and vitamin D receptor (VDR) expression in endometriotic tissue." (PMID 40722678, 2025). "A further six studies assessed levels of expression or single‐nucleotide polymorphism (SNP) variations for DBP or VDR, and how these variations impact endometriosis." (PMID 39739404, 2025). "VDR is also enriched in hyperplastic polypsand endometriosis and in early stages of tumorigenesis.2−5 Causes of VDR overexpression in malignancies, polyps, and otherdisease states are unclear and require further investigations." (PMID 35404047, 2022). "Several studies have found that there is a negative association between the presence of TaqI, FokI, and BsmI VDR polymorphisms and the risk of developing reproductive disorders, such as polycystic ovarian syndrome and endometriosis." (PMID 29892263, 2018). "In the context of reproductive medicine, VDR polymorphisms have been associated with polycystic ovarian syndrome and endometriosis, although these results are inconclusive and require further investigation." (PMID 29892263, 2018). "Similar results were reported by Szczepańska and colleagues (2015), as they did not demonstrate differences in genotype and allele frequencies of several VDR SNPs between 154 women with endometriosis-associated infertility and 347 controls." (PMID 30096760, 2018). "An analysis of VDR gene polymorphisms (ApaI, TaqI, FokI, BmsI) including 132 women with endometriosis and 133 controls found relatively similar VDR polymorphism genotype frequencies in cases and controls." (PMID 22047005, 2011). "The suppressive role of VDR in endometrial stromal cell differentiation also raises intriguing possibilities for its involvement in other processes, such as implantation failure or susceptibility to endometrial disorders like endometriosis." (PMID 41292920, 2025). "Clarifying these points will help determine whether restoring vitamin D sufficiency can modify the pathogenesis or progression of endometriosis and refine VDR-based risk stratification." (PMID 40722678, 2025). "Several studies aimed to address whether DBP and VDR are genetic risk factors for endometriosis‐associated infertility." (PMID 38698459, 2024). "Currently, it is unclear whether elevated endometrial VDR expression is a primary event or a consequence of endometriosis-associated inflammation." (PMID 36578019, 2022). "Given that VDR and AHR were both previously implicated in endometriosis, in this study we investigated the nuclear and cytoplasmic expression of VDR and AHR in tissues from normal endometrium (in the three physiological phases: proliferative, early, and late secretory) and ovarian endometriosis." (PMID 34155552, 2021). "In the endometriosis group, VDR immunohistochemical expression was observed solely in the cytoplasm of stromal and epithelial cells, with no nuclear staining detected." (PMID 40722678, 2025). "In conclusion, this article makes a valuable contribution by advancing our understanding of the VDR-mediated anti-inflammatory role of 1,25(OH)2D3 in endometriosis." (PMID 41360706, 2025). "One study that assessed mRNA expression for various vitamin D‐related factors including VDR, CYP27B1 and the catabolic enzyme 24‐hydroxylase (CYP24A1) in ovarian tissues showed that women with endometriosis had higher expression of VDR, CYP27B1 and CYP24A1." (PMID 39739404, 2025). "We read with great interest the recent article entitled ‘1,25(OH)2D3 alleviates inflammation in endometriosis via VDR-dependent inhibition of the TLR4/NLRP3–NF-κB pathway’." (PMID 41360706, 2025). "In endometriosis, vitamin D exhibits anti-inflammatory and antiproliferative properties, while uterine leiomyomas show reduced VDR expression compared to normal myometrium." (PMID 41394244, 2025).
endometriosis (continued). "This is the first study to investigate the association between vitamin D receptor (VDR) expression and the severity of advanced stage III and IV endometriosis." (PMID 40722678, 2025). "Three studies have assessed the possible differential representation of Fok1, Bsm1, Apa1 and Taq1 SNPs in the VDR gene in women with endometriosis." (PMID 39739404, 2025). "A recent study used the immunoreactivity score (IRS) to evaluate immunohistochemical (IHC) staining for VDR, comparing three phases of normal endometrium in premenopausal women with endometriosis." (PMID 40722678, 2025). "In one study, VDR expression was evaluated in the eutopic and ectopic endometria of 20 women in the control group and 32 women with endometriosis." (PMID 38215179, 2024). "The “Nuclear Receptors Meta Pathway,” listed that vitamin D receptor, VDR, as being represented in our dataset of decidualized cells from donors with endometriosis." (PMID 38402336, 2024). "Studies revealed that variants in the VDR gene and DBP serve as genetic risk factors referring to infertility associated with endometriosis and the pathogenesis of endometriosis." (PMID 38698459, 2024). "Another aspect of vitamin D’s role in endometriosis is indicated by progestin treatment’s direct impact on VDR expression." (PMID 37626598, 2023). "The researchers discovered no cyclic fluctuations in the menstrual cycle phases compared with controls and lower VDR expression in the ectopic endometrium than in the eutopic one in women with endometriosis." (PMID 37626598, 2023). "The researchers further investigated this area by examining VDR expression in endometriotic cyst specimens from women who had received endometriosis diagnoses and contrasting women with treatment with those who had not received treatment." (PMID 37626598, 2023). "There is scarce research that has analyzed the tissue levels of VDR in endometriosis-affected women." (PMID 37626598, 2023). "By showing decreased serum vitamin D levels in endometriosis-affected women, along with raised tissue vitamin D receptor levels in endometriotic specimens, we were able to demonstrate a connection between the two." (PMID 37626598, 2023). "Various immune cells found in endometriosis lesions and known to maintain the disease, have been shown to express VDR and exhibit an active vit D metabolism in other systems." (PMID 36578019, 2022). "The vitamin D receptor (VDR) and aryl hydrocarbon receptor (AHR) are two nuclear receptors which have been associated with endometriosis." (PMID 34155552, 2021). "This study provides a possible starting point for developing more effective drugs specifically targeting VDR- or AHR-expressing cells in the context of endometriosis." (PMID 34155552, 2021). "We did not identify any significant differences in the expression of cytoplasmic VDR in either the normal endometrium or endometriosis (ovarian endometriosis median = 2; p = 0.053, PE median = 4, ESE median = 0, LSE median = 8.2)." (PMID 34155552, 2021). "The comparison of VDR or AHR expression in such tissues is based on the nature of endometriosis, which is defined as “the presence of endometrium-like tissue outside the uterus”." (PMID 34155552, 2021). "For this purpose, an evaluation was performed using tissue from the three normal phases of the endometrium (proliferative, early, and late secretory) and in endometriosis by immunohistochemistry, using anti-VDR and anti-AHR antibodies." (PMID 34155552, 2021). "We demonstrate that in the nuclei of glandular cells in endometriosis, the expression of VDR and AHR is mutually exclusive—when the expression of one receptor is high, the other one is low—suggesting a possible target in the treatment of endometriosis." (PMID 34155552, 2021). "Nonetheless, the expression of epithelial VDR mRNA was higher in the endometriosis group compared to the control group and the same applied to the stromal cell expression." (PMID 30096760, 2018).
endometriosis (continued). "VDR mRNA expression was evaluated by RT-PCR in eutopic endometrium from women with endometriosis (n = 13) compared to that of a control group (n = 14)." (PMID 30096760, 2018). "Recently, it has been suggested that CYP17, VDR, MUC17, COX-2, WNT4, E-cadherin, CYP19, CYP17, TYK2, NFKB1, and MUC2 gene variants also contributed to endometriosis-related infertility." (PMID 28405865, 2017). "The study’s findings may restrict the applicability of VDR as a biomarker for evaluating disease progression across various stages, as it exclusively included participants with advanced endometriosis." (PMID 40722678, 2025). "We aimed to examine the association between vitamin D levels and endometriosis and evaluated VDR expression in endometriotic lesions to explore whether circulating vitamin D levels or tissue VDR expression correlated with the severity of endometriosis." (PMID 40722678, 2025). "We hypothesized that women with endometriosis would have different vitamin D levels compared to controls and that vitamin D levels would correlate with VDR expression in endometriotic lesions." (PMID 40722678, 2025). "Second, given that endometrial tissue contains the VDR and that vitamin D regulates inflammatory and immune responses, it has been hypothesized that vitamin D may play a role in endometriosis." (PMID 38215179, 2024). "Despite these discrepancies, genetic studies have suggested that genetic variants in the VDR and DBP genes may play a role in endometriosis-associated infertility." (PMID 38698459, 2024). "Additionally, to our knowledge, the relationship between PHH3 and VDR tissue expressions in endometriosis-affected women was analyzed for the first time in this study." (PMID 37626598, 2023). "VDR signalling may be an elusive protagonist in the pathophysiology of endometriosis creating opportunities for the development of novel therapeutic targets." (PMID 36578019, 2022). "The endometrium is a very differentiated tissue, and the expression of VDR may contribute to the pathogenesis of endometriosis in terms of induction of endometrial-like differentiation in tissue where endometrial cells should not be present." (PMID 34155552, 2021). "This elevation in VDR, 1α-hydroxylase, and 24-hydroxylase mRNA expression in the endometrium of women with endometriosis suggests an active role of the VDR pathway in the pathogenesis of endometriosis." (PMID 34155552, 2021). "Molecular investigation has also showed that VDR polymorphism did not cause endometriosis or infertility." (PMID 32259002, 2020). "Finally, clinical trials with VD would be helpful to evaluate the possible therapeutic benefit of VD and/or VDR agonists in women with endometriosis." (PMID 30096760, 2018). "Future investigations need to be performed using different models for endometriosis disease, for instance, primate models, to elucidate the real mechanism by which VD and/or VDR agonists may exert an “anti-endometriosis” effect." (PMID 30096760, 2018). "Therefore, this study aimed to enhance our understanding of the role of vitamin D and the vitamin D receptor (VDR) in the pathogenesis of endometriosis, which may inform future preventive and therapeutic strategies." (PMID 40722678, 2025). "In addition to vitamin D, VDR agonists also are applicable to the treatment of endometriosis." (PMID 38698459, 2024). "It is unclear what this means for vitamin D function in endometriosis ovarian tissue, as higher CYP27B1 and VDR would be consistent with improved 25(OH)D conversion to 1,25(OH)2D and subsequent signalling." (PMID 39739404, 2025). "Additionally, vitamin D levels and VDR expression may correlate with endometriosis severity." (PMID 40722678, 2025). "Although analysis of DBP, VDR, 1α‐hydroxylase and 24‐hydroxylase provides a ‘snapshot’ of the vitamin D system in different endometriosis settings, it is not easy to obtain the tissue required to make these types of measurement." (PMID 39739404, 2025).
endometriosis (continued). "The increased expression of VDR in the endometrium of endometriosis-suffering women without therapy shows that the molecular pathway is actively involved in the development and pathophysiology of endometriosis." (PMID 37626598, 2023). "A combined analysis of the possible changes in the relative expression of VDR and AHR is currently missing and could provide more insight into the pathophysiological description of endometriosis." (PMID 34155552, 2021). "Unfortunately, the authors did not study the VDR mRNA expression in the ectopic endometrium of women with endometriosis." (PMID 30096760, 2018). "A nonsignificant trend towards higher levels of VDR mRNA was observed in the endometriosis group (p = 0.10)." (PMID 30096760, 2018). "Contrary to these findings, the results of two studies have indicated that VDR and DBP gene polymorphisms may have no role in endometriosis susceptibility." (PMID 38698459, 2024). "Interestingly, they found VDR downregulation while in the mid secretory phase as opposed to the early secretory phase, but no notable difference was found compared with the proliferative phase in endometrium absence of endometriosis." (PMID 32183826, 2020).